IGLV11-55 (immunoglobulin lambda variable 11-55 (non-functional))
Description:
Probable non-functional open reading frame (ORF) of V region of the variable domain of immunoglobulin light chains. Non-functional ORF generally cannot participate in the synthesis of a productive immunoglobulin chain due to altered V- (D)-J or switch recombination and/or splicing site (at mRNA level) and/or conserved amino acid change (protein level). Immunoglobulins, also known as antibodies, are membrane-bound or secreted glycoproteins produced by B lymphocytes. In the recognition phase of humoral immunity, the membrane-bound immunoglobulins serve as receptors which, upon binding of a specific antigen, trigger the clonal expansion and differentiation of B lymphocytes into immunoglobulins-secreting plasma cells. Secreted immunoglobulins mediate the effector phase of humoral immunity, which results in the elimination of bound antigens. The antigen binding site is formed by the variable domain of one heavy chain, together with that of its associated light chain. Thus, each immunoglobulin has two antigen binding sites with remarkable affinity for a particular antigen. The variable domains are assembled by a process called V-(D)-J rearrangement and can then be subjected to somatic hypermutations which, after exposure to antigen and selection, allow affinity maturation for a particular antigen.
Synonyms: IGLV1155; V4-6
Gene: Immunoglobulin variable (V) gene on chromosome 22 (22,201,663 to 22,202,161, forward strand). Ensembl gene ENSG00000211641.
Subcellular location: Secreted; Cell membrane
Gene Ontology:
Biological process: immune response
Cellular component: extracellular region; immunoglobulin complex; plasma membrane
Homologues: Orthologues: macaque IGLV11-55 (85% identical), zebrafish si:ch211-137i24.12 (29% identical). Paralogues in human: IGLV5-37 (72% identical), IGLV5-45 (66% identical), IGLV5-52 (63% identical), IGLV5-48 (59% identical), IGLV1-40 (52% identical), IGLV2-11 (52% identical), IGLV2-18 (52% identical), IGLV2-8 (52% identical), IGLV3-21 (52% identical), IGLV2-14 (51% identical), IGLV6-57 (51% identical), IGLV2-23 (50% identical), and 81 more.